KRT7 (keratin 7)
Diseases named in the same sentence as KRT7 in open-access papers (continued):
Sharing a sentence is not in itself a finding about the gene and the disease.
cancer (continued). "LCAs derived from adenocarcinomas (ACs) of different patients maintained the intertumoral heterogeneity of cancer cell differentiation degree, and the expression patterns of EpCAM, cytokeratin 7 (CK7) and Ki67 were also retained in the LCAs." (PMID 38643164, 2024). "Established OC cells displayed an upregulated expression of cytokeratin-7/8 (p = 0.0022), commonly occurring in malignant neoplasms." (PMID 38549061, 2024). "The cancer cells were also positive for cytokeratin-7 (CK7), CK19, and CA19-9 but negative for CK20, alpha-fetoprotein (AFP), and carcinoembryonic antigen (CEA)." (PMID 38185762, 2024). "As cytokeratin 7 (CK7) is a specific marker for cancer cells, we examined the metastatic ratio via CK7." (PMID 39227585, 2024). "Through extensive molecular interactions with EMT and the NF-κB signaling pathway, the downregulation of KRT7 was found to inhibit cancer cell migration, as determined by a mechanism analysis." (PMID 37954148, 2023). "KRT7 is abnormally expressed in various types of cancer and promotes the malignant progression of tumors." (PMID 37954148, 2023). "Among them, KRT7 was highly expressed in cancer cells, AEBP1 was mainly expressed in fibroblasts, BCL2A1 and RGS1 were both highly expressed in myeloid cells." (PMID 37996875, 2023). "Specifically, CC-1 represented the epithelial-like cancer cell subpopulation expressing Epcam, Cdh1, and Krt7." (PMID 37190324, 2023). "The combination of cytokeratin 20 (CK20) and cytokeratin 7 (CK7) is of great benefit to the categorization of carcinomas and discrimination of primary adenocarcinomas from metastatic ones." (PMID 37483522, 2023). "KRT7 has been identified as a putative stemness factor related to cancer stem cells in other cancer such as liver cancer." (PMID 35406395, 2022). "PCA loadings show that the genes exerting the largest effects include MMP1 and MMP10, KRT7, and KRT19, high levels of which in other cancers have been associated with unfavorable prognosis." (PMID 35480116, 2022). "In the first case, the m6A deposition in keratin 7 (KRT7), an important mediator of cancer metastases, stimulates its translation via the YTHDF1/eEF1 axis." (PMID 36012237, 2022). "Further immunohistochemical analysis revealed that the cancer cells were positive for CK-Pan, cytokeratin 7 (CK7), cytokeratin 20 (CK20), and partly positive Ki-67." (PMID 35941530, 2022). "Together, these observations emphasize the major but complex and tissue-specific functional implications of KRT7 function in cancer progression." (PMID 35406395, 2022). "Together, these observations emphasize the major but complex and tissue-specific implications of KRT7 function in cancer progression." (PMID 34070214, 2021). "We also detected enrichment for transcripts encoding fibroblast-specific protein 1 (FSP1/S100a4), keratins Krt7, Krt8, Krt14 and Krt18 and claudins Cldn3, Cldn4 and Cldn7 in this cluster which were also enriched in epithelial/cancer cells." (PMID 32455670, 2020). "Second cytology of cervical lymphadenopathywas remarkable for cytokeratin 7 and 20, placental alkaline phosphatase, andCDX2 suggestive of germ line tumor with both mucinous ovarian andgastrointestinal carcinomas." (PMID 31423841, 2019). "The immunohistochemistry showed that the carcinoma cells were positive for cytokeratin 7 (CK7) and thyroid transcription factor-1 (TT1) and negative for cytokeratin 20 (CK20)." (PMID 27217885, 2016). "The carcinomas are characterized with cytokeratin 7 (CK7), cytokeratin 20 (CK20), thyroid transcription factor 1 (TTF-1), estrogen receptor (ER) or prostate-specific antigen (PSA." (PMID 26695546, 2016). "Anti-cytokeratin 7 (CK 7) and anti-cytokeratin 20 (CK 20) antibodies have been used to differentiate between cancers of a primary or metastatic source." (PMID 25883818, 2015). "Cytokeratin 7 positive cancer cells cannot only be found settled in the centre of the microtissue but also scattered in the fibroblast ring and in the periphery of the microtissue." (PMID 24663399, 2014).
cancer (continued). "The expression pattern of cytokeratin 7 positive cancer cells in A549 co-cultures indicates that all α-SMA expressing cells are at the same time cytokeratin 7 negative." (PMID 24663399, 2014). "Immunohistochemically, the carcinoma cells reacted strongly and diffusely with cytokeratin 7, estrogen and progesterone receptors, and GATA3." (PMID 25400965, 2014). "For example, in our analyses, for the KRT7 gene, the same splice site can be classified as normal- or cancer-specific depending on the tissue type considered." (PMID 20813049, 2010). "In good agreement with previous reports, we found that KRT7 expression was highly epithelial cell specific, as the protein exclusively is expressed in either normal urothelial cells or cancer cells derived from urothelial cells." (PMID 16265353, 2005). "Moreover, Hallmark gene set for cancer‐related pathways (e.g., EMT, IL6 and TNFα signals) were exclusively enriched in ALB+KRT7+ EPCs from AC samples." (PMID 39834100, 2025). "Immunohistochemistry has been performed and revealed that the carcinoma was strongly and diffusely positive for cytokeratin 7 (CK7), GATA-binding protein 3 (GATA3), and p40, and was negative for oestrogen receptor (ER), progesterone receptor (PR), and paired box gene 8 (PAX8)." (PMID 40656261, 2025). "Remarkably, all seven DNPCa samples examined exhibited positive KRT7 staining in cancer cells." (PMID 39095562, 2024). "Another cytokeratin, described as a putative heterodimer partner of KRT7, i.e., KRT17, has also been shown to be significantly lower in aggressive cancers (diffuse gastric cancer), similar to the loss of KRT7 staining that we observed in tumoral prostatic glands." (PMID 35406395, 2022). "The literature is scarce and mixed regarding KRT7 regulation in cancer." (PMID 34070214, 2021). "Aberrant expression of KRT7 in budding cancer cells represents a modification of the epithelial phenotype (epithelial–epithelial transition) which may be linked to gains in motility and invasive potential." (PMID 29868478, 2018). "To identify the tissue origin of the carcinoma, we use cytokeratin 7 (CK7), cytokeratin 20 (CK20), thyroid transcription factor 1 (TTF-1), estrogen receptor (ER) in female patients or prostate-specific antigen (PSA) in male patients as the minimal set of markers." (PMID 26695546, 2016). "Therefore, cytokeratin 7 staining, a protein only expressed by cancer cells, was performed to prove that only fibroblasts generated α-SMA in our microtissues." (PMID 24663399, 2014). "Surprisingly, several presumably cancer-specific KRT7 isoforms were observed." (PMID 16265353, 2005). "Further annotation of these cancer cells based on marker gene expression revealed that the non‐proliferating cancer cells could be classified into basal and luminal classes based on the expression of KRT7, marker of basal cells, and GATA3, marker of luminal cells, respectively." (PMID 38582099, 2024). "Notably, cancer samples classified as columnar-like were mainly KRT5low, KRT7high and TP63low, whereas samples classified as squamous-like and undetermined were mainly KRT5high and TP63high with a mixed KRT7 status." (PMID 33462395, 2021). "Within the constructed network, MMP1, KRT7, EGR1, and IL11 played crucial roles, likely due to the cell lines representing invasive and proliferative cancers." (PMID 41590789, 2025). "In the case of the INT type AoV cancer, there is often expression of cytokeratin 20 (CK20), whereas the PB type typically exhibits cytokeratin 7 (CK7) expression." (PMID 38167037, 2024). "Immunofluorescence (IF) staining for the epithelial cell markers cytokeratin 5 and cytokeratin 7 and the transcription factor GATA3 was performed to characterize the three cancer organoid models." (PMID 35805961, 2022). "In fact, EGFR was part of a cluster of dysregulated genes and enriched gene sets in the FIR20 cells that define the basal breast (cancer) subtype (LAMC2, TRIM29, COL17A and cytokeratin genes (KRT6, KRT7, KRT13, KRT15))." (PMID 35579852, 2022).
cancer (continued). "We found that the cancer subtype markers (GRP, CHGB, NEUROD1, and CHGA for NET; KRT5, DSC3, KRT6B, TP63, and KRT6A for SCC; and NKX2-1, KRT7, NAPSA, and MUC1 for ADC) were specifically expressed in the corresponding cancer subtypes." (PMID 35962452, 2022). "Cytokeratin 7 (CK7), which is usually expressed by epithelial cells coating the cavities of internal organs, can assist in the diagnosis of carcinomas." (PMID 36004971, 2022). "Fine needle aspiration biopsy of the axillary lymph node confirmed high-grade carcinoma based on the morphologic features and positive staining for epithelial markers (keratin AE1/AE3, keratin 5/6, keratin 7), GATA 3, and p63." (PMID 35444869, 2022). "Histologic patterns suggestive for progression of some cytokeratin 7 and/or MUC5AC-positive metaplastic lesions into cancer of the same phenotype were also observed." (PMID 33963925, 2021). "We identified 559 cancer cells according to epithelial and cancer markers including KRT19, KRT7, EPCAM, SOX9, and KRT23." (PMID 34326696, 2021). "KRT7, KRT18, KRT19 protein expression in tumors were reported to predict prognosis in several cancer types." (PMID 34070214, 2021). "In contrast to other cancers, STAD showed the least shared factors (n = 3), and only one shared (KRT7 expression) with the gastrointestinal cancer COAD." (PMID 34946814, 2021). "The results were consistent with previous studies that suggested that KRT7 and KRT 81 were expressed at increased levels in several types of cancers and contributed to cancer metastasis." (PMID 34764866, 2021). "Furthermore, KLK4–7 regulate gene expression of other cancer-related factors: simultaneous overexpression of these four KLKs lead, e.g., to a distinct up-regulation of moesin and keratin 19 mRNA and protein expression, while keratin 7 is strongly down-regulated." (PMID 31307411, 2019). "Subpopulation B consisted of 121 cells (29.1%) and showed overexpression of 13 genes, including seven cancer genes (HSPB1, ANXA1, SLPI, KRT8, KRT19, KLK7, and ABL2) and several Keratin genes (KRT8, KRT7, KRT19, and KRT6B)." (PMID 28794488, 2017). "On the other hand, the expression patterns of genes like SFTPB, LAMC2, KRT7 and CLIC6 varied significantly among different cancer types, suggesting that these genes may play context‐dependent roles." (PMID 39828988, 2025). "While KRT7 expression has been detected in various types of cancer, its presence in PCa cells has not been observed until now." (PMID 39095562, 2024). "YKL-40 gene expression was primarily increased in the fibroblast (gene annotation: COL1A, BGN, DCN), myeloid (gene annotation: CD68, LYZ, AIF1), cancer (gene annotation: EPCAM, KRT7, KRT18), and B-cell (gene annotation: CD79A, CD79B) populations in cancer tissue compared to healthy tissue." (PMID 35631632, 2022). "KRT7 was also positively correlated with keratin-8 (KRT8) expression in an intra-cellular gene-gene correlation, with KRT8 having been identified as a pan-cancer early biomarker in a multi-scale integrated analysis." (PMID 35406395, 2022). "Additionally, we verified an immunophenotype comparable to human patient OSPC samples based on the expression of Claudin 3, Claudin 4, Cytokeratin 7, p16, and EMA in SCID pig carcinomas." (PMID 30723704, 2019). "On immunohistochemistry, the carcinoma cells were positive for cytokeratin 7 (CK7), CA 19-9, and EMA, and negative for CK20, α-fetoprotein, and thyroid transcription factor-1 (TTF-1)." (PMID 31432273, 2019). "Out of 74 cancer specimens, 26 (35.1%) displayed a diffuse Krt7 immunoreactivity and an absence of Krt20/CDX2 expression." (PMID 29700411, 2018). "In concordance with previously reports, KRT7 was completely absent in stroma cells, but cytoplasmic expressed in most normal urothelial (85%) and all cancer cells (100%)." (PMID 16265353, 2005).
cancer (continued). "Moreover, claudin-18 (≥1%) was positively associated with cytokeratin 7 (CK7) and MUC5AC expression, showing CK7+/MUC5AC+ carcinomas the highest rate of positive cases, whereas a negative correlation was found between claudin-18 and CDX2 expression." (PMID 35925388, 2022).
adenocarcinoma (219 papers, 2002 to 2026). A common cancer characterized by the presence of malignant glandular cells. "However, SSA have been linked to adenocarcinomas with microsatellite instability (MSI) with a positive immunostaining for Cytokeratin 7 (CK7) and mostly localized in the proximal colon." (PMID 24209454, 2013). "Immunohistochemistry revealed adenocarcinoma cells positive for thyroid transcription factor-1, Napsin A, and cytokeratin 7, supporting a pulmonary origin." (PMID 41416296, 2025). "In the present case, adenocarcinoma cells were immunoreactive only for low molecular weight cytokeratin- Keratin 7 while immunonegative for all other epithelial markers like EMA,p63 and high molecular weight cytokeratin-Keratin5/6." (PMID 40822511, 2025). "She had a liver biopsy of the hepatic lesion, which revealed an adenocarcinoma with expression of cytokeratin 19, cytokeratin 7, N-cadherin, and high expression of carbonic anydrase IX." (PMID 39330010, 2024). "Liver biopsies revealed an adenocarcinoma with expression of cytokeratin 19, cytokeratin 7, N-cadherin, and high expression of carbonic anydrase IX." (PMID 39330010, 2024). "Ultrasound-guided biopsy identified the mass as an adenocarcinoma, with positive staining for cytokeratin 7 (CK7), GATA-3, a transcription factor important in the regulation of certain genes, and p40, a marker of squamous differentiation." (PMID 33198722, 2020). "The pathological analysis of the lymph node specimen biopsy indicated adenocarcinoma with cytokeratin 7 and thyroid transcription factor-1 positivity." (PMID 30443294, 2018). "The pathological study showed a 9 cm-sized lepidic predominant adenocarcinoma (pT3N0M0), with necrotic and hemorrhagic changes due to the embolization, and Cytokeratin 7 (CK7) and TTF-1 positive IHC staining." (PMID 29631581, 2018). "Immunohistochemical staining for cytokeratin 7 and 20 revealed that the adenocarcinoma had metastasized from the reconstructed gastric tube." (PMID 30363593, 2015). "The adenocarcinoma component was strongly positive for cytokeratin 7 and pancytokeratin, weakly positive for synaptophysin and CD56, and negative for carbonic anhydrase IX, CD99, CDX2, chromogranin, cytokeratin 20 and smooth muscle actin." (PMID 19523243, 2009). "A scrotal skin biopsy revealed a poorly-differentiated adenocarcinoma, immunohistochemically positive for cytokeratin 7 (CK7) and for thyroid transcription factor 1 (TTF-1), and negative for CK20." (PMID 18801198, 2008). "On immunohistochemical analysis, the adenocarcinoma cells showed diffuse strong immunopositivity for Keratin 7 while immunonegativity for EMA, Keratin 5/6, p63, p40, Androgen receptor (AR), gross cystic disease fluid protein 15 (GCDFP-15), Her2Neu, BerEp4, S100, SMA and calponin." (PMID 40822511, 2025). "In addition, being positive for keratin 7 suggested the presence of an adenocarcinoma." (PMID 27537551, 2016). "Consistently, EP1 and EP2 show high expression of KRT7 and low expression of KRT5 at protein level, further supporting the adenocarcinoma origin." (PMID 41356800, 2026). "Adenocarcinoma was immunohistochemically positive for pancytokeratin (AE1/AE3), cytokeratin 7 (CK7), cytokeratin 20 (CK20), and carcinoembryonic antigen (CEA)." (PMID 37927686, 2023). "Immunohistochemical staining was carried out to examine the expression of cytokeratin 7, cytokeratin 20, and caudal-related homeobox transcription factor 2 (CDX2) to determine the origin of the adenocarcinoma." (PMID 36532640, 2022). "The adenocarcinoma marker cytokeratin-7 (CK7) and CXCR4 IHC staining further verified the liver lesions as adenocarcinoma that exhibited CXCR4 expression." (PMID 35145271, 2022).
adenocarcinoma (continued). "We examined the expression of two adenocarcinoma markers, thyroid transcription factor (TTF-1) and Napsin A, as well as luminal epithelial marker cytokeratin 7 (CK7)." (PMID 32771979, 2020). "Given her smoking history, imaging characteristics, and the TTF-1 and cytokeratin 7 (CK7) positivity of her staining pattern, the diagnosis is consistent with an adenocarcinoma of pulmonary origin." (PMID 29900025, 2017). "The histological diagnosis was poorly differentiated adenocarcinoma (pT2aN0M0, stage IB), with positive Thyroid Transcriptional Factor-1 (TTF-1) and Cytokeratin 7 (CK7)." (PMID 27829227, 2016). "Histology of both the primary tumor and the perianal nodule revealed a well-differentiated adenocarcinoma with cytokeratin 20 (CK20)+ and cytokeratin 7 (CK7)- staining." (PMID 23033985, 2012). "Ultrasound-guided puncture confirmed the nodule to be poorly differentiated adenocarcinoma, positive in cell keratin 7 (CK7)、CK20 and CDX-2, and negative in Hepatocyte and CgA." (PMID 34856986, 2021). "Cytokeratin 7 (CK7) and Cytokeratin 20 (CK20) are reliable and well-characterized immunohistochemical markers, and are usually helpful in distinguishing intestinal type and pancreaticobiliary type adenocarcinoma." (PMID 26603157, 2015). "The results of immunohistochemical assessments showed that Thyroid transcription factor 1 (TTF-1 or NKX2–1) and Cytokeratin 7 (CK7), which are sensitive and specific expressions (positive rate more than 70%) in NSCLC and especially in adenocarcinoma, were all significant positive." (PMID 25474437, 2014). "The histological examination of the right hemicolectomy specimen revealed an adenocarcinoma in caecum staining positive for Cytokeratin 7 and Carcinoembryonic antigen and negative for Cytokeratin 20, CDX2 and Estrogen receptor." (PMID 18471290, 2008). "Immunohistochemical staining demonstrated that the adenocarcinoma cells were positive for thyroid transcription factor-1, Napsin A, cytokeratin 7, and epithelial membrane antigen (EMA), and negative for cytokeratin 20, findings consistent with pulmonary origin." (PMID 41416296, 2025). "Immunohistological analysis demonstrated that the adenocarcinoma cells were positive for cytokeratin 20 (CK20) and negative for cytokeratin 7 (CK7) and positive for caudal type homeobox transcription factor 2 (CDX2)." (PMID 27473859, 2016).
infection (17 papers, 2008 to 2025). The state of being infected such as from the introduction of a foreign agent such as serum, vaccine, antigenic substance or organism. "The third pathway involves hrHPV infection of the specific stretch of endocervical, keratin 7‐positive cuboidal cells at the SqCJ, producing immediately a HSIL without a low‐grade precursor lesion." (PMID 32644288, 2020). "Infection of these cell types was confirmed by double immunostaining for cytokeratin 7 and CD31 (data not shown)." (PMID 19115001, 2008). "Immunofluorescence demonstrated co-localization of virus and cytokeratin 7, a marker for biliary epithelium, on PI days 5 and 7 for the early and late infection groups, indicating that the biliary epithelium was the specific target of RRV binding and infection." (PMID 23844248, 2013).
gynecologic tumors (2 papers, 2022 to 2026). "Immunohistochemistry was positive for PAX8 and cytokeratin-7, suggesting a gynecological origin, although no primary gynecological tumor was identified on imaging." (PMID 41684973, 2026).